IL10 (interleukin 10)
Diseases named in the same sentence as IL10 in open-access papers (continued):
Sharing a sentence is not in itself a finding about the gene and the disease.
infection (continued). "In contrast, IL-4, IL-10 and IL-13 act as downregulators of the cellular immune response, inhibiting T-cell proliferation, and are associated with impaired infection control and a poor outcome." (PMID 28486489, 2017). "It has been shown that IL-10-derived from B cells is capable to promote the development of suppressive responses associated with susceptibility to infection." (PMID 28626451, 2017). "In multi-marker analysis, the same and further TH1-related and pro-inflammatory biomarkers were inversely associated with infection, whereas angiogenic chemokines and IL-10 were positively associated." (PMID 28628613, 2017). "The hallmark of this infection-induced host immunodeviation is the characteristic high levels of the regulatory interleukin-10 (IL-10) cytokine." (PMID 28626451, 2017). "We observed that the production of IL-10 was required by S. Typhimurium to cause a systemic disease, since mice lacking IL-10 (IL-10−/−) were significantly more resistant to die after an infection as compared to wild-type (WT) mice." (PMID 28824622, 2017). "As a potent anti-inflammatory cytokine, IL-10 also inhibits IL-27 production during infection-associated inflammation." (PMID 29021521, 2017). "In a S. epidermidis DRI mouse model it was shown that IL-10 was involved in reducing infection-associated morbidity, with higher levels of pro-inflammatory cytokines and greater weight loss in IL-10 KO animals." (PMID 28824556, 2017). "IL-10 deficient mice were able to clear the infection, but had persistent lung inflammation and enhanced morbidity after infection." (PMID 27066459, 2016). "During the acute phase of infection (5–14 days post-infection), IL-10−/− mice demonstrated significant deficiencies in many behavioural tests when compared to infection-matched WT mice." (PMID 27557867, 2016). "In conclusion we can state that maternal filarial infection during pregnancy increases the susceptibility of children to infection by immune priming through expression of Tregs as well as regulatory cytokine IL-10." (PMID 27861499, 2016). "IL-10 regulated parasite progression and development of infection have been linked with accumulation of CD4+CD25+ regulatory T cells (Treg) in both experimental and human cutaneous leishmaniasis (CL)." (PMID 26829554, 2016). "Intereukin-10 is known to be produced by the host upon infection with C.albicans hyphae and increased levels of IL-10 have been associated with increased susceptibility to candidiasis." (PMID 27411776, 2016). "For the delivery sub-group, infection at delivery was associated with a significantly diminished level of IL-10 in response to both PHA and DBL-5, as well as a significantly reduced frequency of DBL5-specific IFN-γ-producing CD4+ T cells in MI versus UI." (PMID 27653505, 2016). "With epitope and flanking region mutations, the magnitude of AV9, GI11, OLP-45 and IL10 epitopes were all reduced at 1 year post infection, and only OLP-10 in subject 3 was slightly increased." (PMID 27577610, 2016). "Inducible Treg (iTreg) cells are produced in the periphery and exert their suppressive activity mainly by producing IL-10, which are significantly linked with hyporesponsiveness and susceptibility to infection." (PMID 27893414, 2016). "In the present study, the evaluation of IL-10 demonstrated a possible association with events related to the susceptibility to infection by L. chagasi; the “Control” group has presented increased amounts during the late (T885) post-challenge period." (PMID 27556586, 2016). "IL-10 also significantly influences the course of human malaria infection, with genetic polymorphisms in the IL-10 gene being associated with protection or susceptibility to infection." (PMID 26459508, 2016). "Infection of IL-10-deficient (IL-10−/−) mice with r3LCMV GFP/IL-10 resulted in a large number of hybridomas producing antibodies to IL-10 after a single immunization that after boosting resulted in several high-affinity clones specific to IL-10." (PMID 27447662, 2016).
infection (continued). "In contrast, in the same FMDV-negative cattle, the level of IL-10 mRNA expression within mucosa-associated lymphoid follicles was significantly lower than that in animals that were still carrying the infection (Holm's method-adjusted P value, ≤0.001)." (PMID 27147736, 2016). "The AV9 epitope in subject 4 and the IL10 epitope in subject 12 had mutations at 1 year post infection." (PMID 27577610, 2016). "By suppressing pro-inflammatory responses elicited by various immune cells, IL-10 limits tissue damage and immunopathology caused during infections." (PMID 27337042, 2016). "In fact, it is known that IL-10 can moderate infection-associated immune pathology linked with strong Th1 responses." (PMID 27481240, 2016). "This indicates that memory Ag-experienced CD4+YFP+GFP− T cells are predisposed and programmed toward rapid induction of IL-10 following reactivation during secondary infection." (PMID 27630165, 2016). "The authors showed that NE and Epi signaling through peripheral blood monocyte β2-adrenergic receptors caused an increase in circulating IL-10 concentrations, deactivation of circulating monocytes, and subsequent immunosuppression and infection." (PMID 26883121, 2016). "To confirm this T helper phenotype, we performed intracellular cytokine staining (ICS) for Th1 (IFN-γ), Th2 (IL-13), Th17 (IL-17A) and Treg (IL-10) associated cytokines in polyclonally stimulated lung leukocytes on day 7 post-infection." (PMID 27683080, 2016). "It was found that IL-10 transferred from an STH-infected mother to the unborn child was a predisposing factor for early childhood infection." (PMID 25888883, 2015). "IL-10 produced by B-1CDP cells is the key to understanding their increased susceptibility to infection." (PMID 25933287, 2015). "SNPs in immune-related genes encoding for interleukin-10 (IL-10) have been reported to play role in HCV-related infection; however, the role of IL-10 in HCV infection is debatable." (PMID 25781918, 2015). "To confirm that the production of IL-10 is involved in the susceptibility to infection by L. major, we used B-1CDP cells from IL-10 KO mice." (PMID 25933287, 2015). "This phenotype resembles that of the Card9−/− mice; however, these animals presented with greater pathology, and all of the animals died shortly after infection, a severity that was linked to defects in IL-10 production." (PMID 25674984, 2015). "Increased local levels of several important proinflammatory cytokines, including TNFα, MIP-1α, IL-12 and IL-10, were associated with a decreased likelihood of elimination of the virus in women with established long-term infection." (PMID 25663851, 2015). "In this model of murine leishmaniasis, T cell or B cell derived IL-10 production has also been implicated in the progression of infection." (PMID 25955652, 2015). "The present paper provides evidence of the association of IL-10 response during the acute phase of infection with a common outcome of FMD disease (i.e. persistence) in cattle." (PMID 26582423, 2015). "At 4 weeks post-infection, Th1-associated Ifng, Cxcl10, and Il12 transcript levels were significantly higher in joints of Il10-/- and DKO mice, compared to transcript levels in joints of B6 and Mir155-/- mice." (PMID 26252010, 2015). "Previous studies clearly demonstrated that IL-10-deficient mice rapidly succumb to infection by T. gondii, because of extensive necrosis of the liver, lungs, and intestines, which was attributed to an uncontrolled Th1 response." (PMID 26575028, 2015). "The level of mRNA encoding 4 interleukins (Il10, Il11, Il1rn, Il1a) was increased and 1 interleukin (Il18) decreased in vaginal tissue collected at 35 days post-infection." (PMID 26779389, 2015). "The Fas- and FasL-deficient mice showed significantly decreased levels of IL-10 expression early during infection (3rd and 7th d.p.i) in comparison to wild-type mice (P ≤ 0.001), followed by significantly decreased mRNA levels of TGF-β1 at 7th and 10th d.p.i." (PMID 25873756, 2015).
infection (continued). "IL-10 knockout mice are at greater risk of some pregnancy pathologies that occur in response to infection." (PMID 26106385, 2015). "This IFN-γ surge is followed by a sudden decrease, most likely associated with a control of the infection, as indicated by a corresponding drop of IL-10 and TNF-α concentration in the serum." (PMID 26566996, 2015). "Previous C. jejuni infection studies revealed that the murine gnotobiotic IL-10−/− model is well suited not only to study pathogenic colonization properties, but also infection-induced immunopathological responses mimicking key features of human disease." (PMID 26483849, 2015). "We found significantly lower levels of IL-10 during the acute (p = 0.0154) and post-acute (p = 0.0207) phases of infection associated with the MHC class II M3 haplotype (n = 13)." (PMID 24695530, 2014). "Infection of B cells by EBV results in expression of virus-encoded IL-10 (vIL-10, encoded by the BCRF1 gene) as well as induction of the endogenous cellular IL-10 (cIL-10) gene." (PMID 25324959, 2014). "The exacerbated release of IL-10 by Yersinia plays a crucial role in the pathogenesis since IL-10-deficient mice are resistant to the infection." (PMID 24119189, 2014). "In comparison, IL10 has fewer complications yet is still associated with a number of adverse reactions such as increased infections, anemia, and headache." (PMID 24736312, 2014). "Recently, research has shown that IL-10 and related cytokines can facilitate the tissue-healing process in injuries caused by infection or inflammation." (PMID 24478702, 2014). "Given that infection with helminth parasites is associated with the generation of regulatory IL-10 secreting Bregs, we further characterised this expanded B cell population." (PMID 24466007, 2014). "The present study reports for the first time the relationship between urinary cytokines IL-6, IFN-γ, TNF-α and IL-10, and S. haematobium infection and infection-associated urinary tract pathology in primary school children." (PMID 25223302, 2014). "Subsequently we showed that intramuscular vaccination with LaSP-Sol leads to enhanced susceptibility to infection, in a manner associated with its capacity to stimulate IL-10 and TGF-beta production by immune cells from 7-day infected mice." (PMID 25239157, 2014). "Considering our observations and these previous reports, we think that the high hepatic bacterial load seen in TLR2-deficient mice at the late phase of infection (3 d post-infection) was due to a lasting decrease in IL-10 release." (PMID 24058538, 2013). "Taken together, IL-10 secretion by T cells has an influence on immune activation early after infection and is sufficient to render BALB/c mice susceptible to an uncontrolled Leishmania major infection." (PMID 23825956, 2013). "Later on, it was shown that IL-10 knockout mice are more susceptible to infection and have higher mortality rates than wild-type mice." (PMID 24260222, 2013). "We have previously employed a specific murine model that involves infection of IL-10-deficient mice (IL10-/- C57BL/6) with Helicobacter hepaticus." (PMID 24450737, 2013). "Susceptibility to infection seems to be associated by the ability of T. cruzi to drive dendritic cells (DC) towards a regulatory IL-10-producing phenotype." (PMID 24260222, 2013). "It is well established that the severe forms of infection are associated with elevated production of anti-inflammatory or suppressive cytokines such as IL-10." (PMID 24205424, 2013).
infection (continued). "Using T cell-specific and macrophage-specific mutant mice, we demonstrate that abrogating the secretion of the immunosuppressive cytokine IL-10 by T cells is sufficient to render otherwise susceptible mice resistant to an infection with the pathogen." (PMID 23825956, 2013). "The same group also showed that infections of IL-10/IL-4 and IL-10/IL-12 double deficient mice in comparison to mice with singular deficiencies led to severe immune polarizations to TH1 and TH2, respectively." (PMID 23429492, 2013). "The induction of IL-10 producing Tregs is associated with a beneficial outcome to the host in this infection model." (PMID 24386207, 2013). "Other markers like serum interleukin-6 (IL-6) and interleukin-10 (IL-10) levels have been associated with more severe infection, multiple organ dysfunction and lethal outcome." (PMID 23374857, 2013). "Infection of IL-10 deficient mice with T. gondii or T. cruzi leads to increased control of the pathogen, but simultaneous increased pathology." (PMID 23555256, 2013). "In experimental Mtb infection, IL-10 has been shown to inhibit host protective anti-microbial mechanisms and thereby enhance susceptibility to infection." (PMID 23544075, 2013). "It has been shown previously that complete IL-10-deficient mice on the naturally susceptible BALB/c background are able to control an infection with L. major." (PMID 23825956, 2013). "The reduced growth and inflammation in agsΔ infections was associated with an increase in the expression of the gene coding for the anti-inflammatory IL10 and a decreased expression of the gene coding for the pro-inflammatory TNFα in the lungs." (PMID 24244155, 2013). "Our finding showing reduced IL-10 production in pDC depleted mice associated with increased lung pathology after Cpn infection advocate a beneficial role for IL-10, at least partially in this model." (PMID 24386207, 2013). "CBA/J mice also have elevated amounts of IL-10 during Mtb infection, contributing to their increased susceptibility to infection." (PMID 23472214, 2013). "We have already shown that IgG, when bound to L. mexicana amastigotes, can induce IL-10 from macrophages stimulated with lipopolysaccharide, and that IL-10 is required for chronic disease caused by infection with this parasite." (PMID 23675550, 2013). "A study on P. knowelsi-inoculated olive baboons reported association between increased levels of IL-4, IL-10, IgM and IgG with increased protection against knowlesi-infection." (PMID 24354660, 2013). "We reasoned that the critical IL-10 associated with the induction of increased pathology was produced relatively early after infection." (PMID 23555256, 2013). "IL-10 impairs macrophage function in transgenic mice infected with mycobacteria and causes them to be susceptible to the infection." (PMID 24350246, 2013). "The deleterious role of IL-10 in diverse models of infection with pathogenic fungi has been intensively studied." (PMID 24205424, 2013). "It was demonstrated that L. major phosphomannomutase (PMM) deficient mutants were able to protect susceptible mice against infection via an increased magnitude of T cell responses and suppression of IL-10 and IL-13 production early during infection." (PMID 23554800, 2013). "During the further course of disease, the T cell-specific as well as the complete IL-10-deficient BALB/c mice were able to control the infection." (PMID 23825956, 2013). "Immunological characterisation of CVL reveals cellular and humoral immune responses comparable to human infection, including immune dysregulation and increased IL-10 which is associated with disease manifestation and progression." (PMID 23554800, 2013). "For the intrinsic pathway, the ADE of DENV infection triggers IL-10 production through an immune complex associated with the Fcγ receptor to enhance the infection severity." (PMID 23800014, 2013).
infection (continued). "Even though B. abortus infected macrophages are capable of producing IL-10 in vitro, only B cells have been implicated as a potential source of IL-10 during in vivo infection." (PMID 23818855, 2013). "IL-10-deficient mice exhibited an augmented migration of these cell types in the beginning of infection, whereas at later time points the presence of these cell populations was more pronounced in IL-10-sufficient mice." (PMID 24205424, 2013). "This healing phenotype was associated with an increased inflammation early after infection, similar to T cell-specific IL-10-deficient C57BL/6 mice." (PMID 23825956, 2013). "IL-10-secreting Th1 cells have been shown to expand during infections, have been associated with the control of allergy and autoimmunity and are believed to result from cytokine synthesis switching in effector T cells." (PMID 24115950, 2013). "Our data suggest that maternal STH infections increase susceptibility to infection during early childhood, an effect that was associated with elevated IL-10 in cord plasma." (PMID 22848773, 2012). "Induction of IL-10 production upon infection of THP-1 macrophages was associated with increased phosphorylation of the MAP Kinases p38 and ERK1/2, which was abolished in the presence of the pharmacological inhibitors SB203580 and PD98059." (PMID 23284742, 2012). "Results revealed that low levels of IL-10 in lungs of mice were associated with severe lung pathology (r = −0.70, p<0.05) at the first day of infection." (PMID 22347396, 2012). "For example, IL-10-producing B cells in L. major-infected BALB/c mice are essential in suppressing type 1 responses that are necessary to clear infection and S. mansoni-infected B cell-deficient μMT mice show more extensive hepatic granulomas." (PMID 22347409, 2012). "Production of interleukin-4 (IL-4) in Leishmania major infection, regulatory T cells in L. mexicana infection, and IL-10 in infection of various species are all associated with susceptibility." (PMID 22448168, 2012). "Our previous observations demonstrated that IL-10 deficiency leads to inflated cellular and cytokine responses in the liver during this infection." (PMID 22880122, 2012). "IL-10 blocks the production of proinflammatory cytokines during the resolution period of infection and consequently reducing the immunopathology caused by these cytokines." (PMID 22880122, 2012). "Our study has demonstrated that the increased population of Tregs in PRRSV-infected pigs at day 2 post-infection is associated with an increased production of IL-10." (PMID 22340040, 2012). "Further to this, we found a clear association with the severity of infection and levels of the anti-inflammatory cytokine IL-10." (PMID 22347396, 2012). "IL10, which encodes an anti-inflammatory cytokine that limits local cytokine-induced tissue damage and systemic inflammatory responses during infection, was upregulated at 2 hours and 24 hours post-challenge." (PMID 22384131, 2012). "Plasma IL-10 increased significantly in children with previous episodes or current infection, and higher levels of IL-12 and IL-13 were also associated with previous episodes." (PMID 22280502, 2012). "Our data clearly demonstrate that following B. microti infection, B cells secrete IL-10, which influences the susceptibility of infection with B. microti." (PMID 23071588, 2012). "The levels of CXCL1, CXCL10, CCL1, CCL3, IFN-γ, TNF-α and IL-6 were significantly increased in the lungs of RSV-infected IL-10-deficient mice compared to control mice on day 8 post infection." (PMID 22393401, 2012). "IL-27R deficient mice develop severe immunopathology in several infection and autoimmune models because of excessive inflammation, reminiscent the phenotypes of IL-10 and IFNAR deficient mice." (PMID 22163016, 2011).